ENSG00000265118 (novel protein)
Gene: Protein-coding gene on chromosome 17 (31,305,213 to 31,318,831, reverse strand). Ensembl gene ENSG00000265118.
Genetic constraint (gnomAD): Loss-of-function variants: 10 observed, 12.1 expected, observed/expected ratio (o/e) 0.83, 90% interval 0.51 to 1.4. Missense variants: 189 observed, 196.1 expected, observed/expected ratio (o/e) 0.96, 90% interval 0.86 to 1.09. Synonymous variants: 56 observed, 70.86 expected, observed/expected ratio (o/e) 0.79, 90% interval 0.64 to 0.99.